PDGFRA (platelet derived growth factor receptor alpha)
Diseases named in the same sentence as PDGFRA in open-access papers (continued):
Sharing a sentence is not in itself a finding about the gene and the disease.
squamous cell carcinoma (3 papers, 2019 to 2024). A carcinoma arising from squamous epithelial cells. "Moreover, downregulation of AR in PDGFRα+ fibroblasts from squamous cell carcinomas induces the activation of cancer-associated fibroblasts, which remodel the ECM within the tumor microenvironment." (PMID 39292748, 2024). "High stromal PDGFRα expression was an independent predictor of increased survival in the overall populations and SCC (squamous cell carcinoma) subgroups of both investigated cohorts." (PMID 31308421, 2019).
Thrombocytopenia (3 papers, 2013 to 2022). A reduction in the number of circulating thrombocytes. "SNP rs1800812 in PDGFRα GG carriers was significantly more frequent in patients with thrombocytopenia (OR 5.2, 95% CI 1.3–21.8, p = 0.02)." (PMID 29581831, 2018).
thymic carcinoma (3 papers, 2014 to 2022). Thymic carcinoma (TC) is a type of thymic epithelial neoplasm characterized by a high malignant potential. "In this study, frequently mutated genes in thymic carcinomas included KIT, DDR2, PDGFRA, ROS1, and IGF1R." (PMID 35884448, 2022). "The expression of PDGFRA was significantly increased in thymic carcinomas as compared to type A and B3 thymomas." (PMID 27844328, 2017). "A further study reported PDGFRA protein expression in all 26 thymomas of various subtypes and 10 thymic carcinomas analyzed." (PMID 27844328, 2017). "An efficacy of the multi-target tyrosine kinase inhibitors sorafenib and sunitinib that block also PDGFRA has been observed in thymic carcinomas." (PMID 27844328, 2017). "In our study the expression of PDGFRA was increased in thymic carcinomas as compared to type A and B3 thymomas." (PMID 27844328, 2017). "PDGFRA was increased in thymic carcinomas and PD-L1 in B3 thymomas and thymic carcinomas." (PMID 27844328, 2017). "Immunohistochemistry was performed to study the expression of ALK, HER2, HER3, MET, phospho-mTOR, p16INK4A, PDGFRA, PDGFRB, PD-L1, PTEN and ROS1 in type A and B3 thymomas and thymic carcinomas." (PMID 27844328, 2017). "Type A and B3 thymoma and thymic carcinoma tissues were stained with antibodies to ALK, HER2, HER3, MET, phospho-mTOR, PDGFRA, PDGFRB, PD-L1, p16INK4A, PTEN and ROS1 to identify potential targets for therapy." (PMID 27844328, 2017).
triple-negative breast carcinoma (3 papers, 2014 to 2022). An invasive breast carcinoma which is negative for expression of estrogen receptor (ER), progesterone receptor (PR), and human epidermal growth factor receptor 2 (HER2). "In the triple negative breast cancer, immunohistochemical expression of C-kit and mutations of PDGFRA are frequent suggesting that they are good candidates for molecular targeted therapy." (PMID 27911271, 2017). "In this study, SUSD4 was found to interact with the tyrosine-kinase receptors EGFR and PDGFRα in triple negative breast cancer cell lines." (PMID 36578014, 2022). "Protein expression and gene copy number of c-KIT, VEGFR2 and PDGFRα in relation to triple-negative breast cancer (TNBC)." (PMID 25025175, 2014).
type 1 diabetes (3 papers, 2018 to 2023). "On the contrary, a high abundance of PDGFRα+ cells in the colon muscle layer in STZ-induced type 1 diabetes was observed in some studies." (PMID 36837509, 2023).
ulcer (3 papers, 2013 to 2022). "The expression levels of PDGFRα and Nrp2 in the mesenchymal cells were higher than the epithelial cells in cardia, cecum, colon, sigmoid, and rectum, especially in the areas with ulcers." (PMID 35027044, 2022). "The expression levels of PDGFRα and Nrp2 in the mesenchymal cells were higher than that in the epithelial cells in cardia, cecum, colon, sigmoid, and rectum, especially in areas with ulcers." (PMID 35027044, 2022). "We found that PDGFRα and Nrp2 all expressed in the epithelial cells and mesenchymal cells, and the expression levels of PDGFRα and Nrp2 in the mesenchymal cells were higher than those in the epithelial cells in cardia, cecum, colon, sigmoid, and rectum, especially in areas with ulcers." (PMID 35027044, 2022).
undifferentiated pleomorphic sarcoma (3 papers, 2019 to 2025). An undifferentiated soft tissue sarcoma characterized by the presence of a pleomorphic malignant cellular infiltrate. "We present genomic analysis of a radiation-induced intracranial undifferentiated pleomorphic sarcoma in an 83-year-old woman with notable KIT and PDGFRA alterations." (PMID 33747576, 2021).
adenosquamous carcinomas of the cervix (2 papers, 2009 to 2012). "The aim of this study was to investigate the presence of EGFR, PDGFRA and VEGFR2 RTKs aberrations, namely overexpression and activating gene mutations in a cohort of 30 adenosquamous carcinomas of the cervix." (PMID 19563658, 2009). "This is the most extensive analysis of EGFR, PDGFRA and VEGFR2 in cervical adenosquamous carcinomas." (PMID 19563658, 2009).
anaplastic ependymoma (2 papers, 2015 to 2023). Anaplastic ependymoma is a rare, malignant type of ependymoma that most often arises in the supratentorial region of the brain of children and young adults and that manifests with variable symptoms including headaches, nausea, vision impairment, memory loss and difficulty walking. "Notably, synonymous variants found in this tumor were detected in other tumors, such as APC (rs41115) variant in MPE, FGFR3 (rs7688609), PDGFRA (rs1873778), and RET (rs1800861) in anaplastic ependymoma Grade III tumor, a-CPP, and myxo-papillary ependymoma (MPE) tumors." (PMID 37273678, 2023).
anencephaly (2 papers, 2017 to 2018). A rare neural tube defect during pregnancy, resulting in the absence of a large portion of the brain and skull in the fetus. "This study highlights the potential involvement of PCP genes including CELSR1 in association with anencephaly phenotypes, and also PDGFRA as strong NTD candidates in humans." (PMID 29205322, 2018).
Arthritis (2 papers, 2020). Inflammation of a joint. "Inspection of the neighborhood on the BN suggests that PDGFRA regulate LPAR1 which may contribute to development of arthritis via cellular infiltration." (PMID 32565911, 2020). "In the present study, several proteins, including ECM1, TGF-β2, PDGFRA, and SAA, that regulate the proliferation of human arthritis were upregulated at both the mRNA and protein levels." (PMID 32318048, 2020).
Ataxia (2 papers, 2020 to 2023). Ataxia refers to impaired coordination of voluntary muscle movement. "In mice, postnatal Pdgfrα-dependent expression of the orthologous murine mutant protein resulted in recessive phenotypes including severe hypomyelination leading to ataxia, tremor, seizures and limited survival, as well as hypodontia and craniofacial abnormalities." (PMID 37635302, 2023).
atherosclerosis (2 papers, 2016 to 2022). A disease characterized by the build-up of fatty material and calcium deposition in the arterial wall resulting in partial or complete occlusion of the arterial lumen. "Interestingly, the cultured SMCs displayed decreased level of PDGFRα suggesting that sustained exposure of oxLDL is the prerequisite for SMC activation as evident in the chronic phase of atherosclerosis." (PMID 35531433, 2022). "Moreover, a seminal article recently reported the intimate involvement of PDGFRα-positive SMCs in the pathology of atherosclerosis by promoting NIH." (PMID 35531433, 2022). "The increased level of PDGFRα in oxLDL-treated carotid vessels indicates the sustenance of SMC activation and progressive NIH during the chronic phase of atherosclerosis." (PMID 35531433, 2022). "The eight major genes upregulated in the carotid vessels (IL18, PDGFRA, IL17, LOX1, TLR4, MYF5, IL1B, and PDPN) were intimately involved in the pathologic progression of atherosclerosis and NIH." (PMID 35531433, 2022).
bladder pain syndrome (2 papers, 2022). "PDGFRα + interstitial cells may contribute to bladder dysfunction conditions such as interstitial cystitis/bladder pain syndrome (IC/BPS) or overactive bladder (OAB)." (PMID 35528149, 2022). "Studies suggest that PDGFRα+ LP interstitial cells may also contribute to bladder dysfunction (e.g., interstitial cystitis/bladder pain syndrome, IC/BPS) because preclinical rodent models show increased expression of interstitial cell markers." (PMID 35645740, 2022).
cardiomyopathy (2 papers, 2023 to 2024). A disease of the heart muscle or myocardium proper. "We have previously shown that activation of the PDGFRA signaling pathway is a likely pathogenic signaling regulator in the pathogenesis of FLNC-related cardiomyopathy and that treatment with crenolanib, an FDA-approved PDGFRA inhibitor, attenuates the arrhythmic phenotype of FLNCKO hiPSC-CMs." (PMID 38334670, 2024). "Microvascular network growth and the angiogenic properties of the TAT in elderly patients with cardiomyopathy also seem to involve the upregulation of PDGFC, FGF2, NOTCH2, FOS, JAG1, and PDGFRA target genes." (PMID 37833902, 2023).
cervical tumors (2 papers, 2006 to 2009). "The objective of this study was to investigate EGFR, PDGFRA and VEGFR2 RTKs overexpression and activating gene mutations in a cohort of 30 adenosquamous carcinomas of the uterine cervix." (PMID 19563658, 2009).
cholangiocarcinoma (2 papers, 2013 to 2025). A carcinoma that arises from the intrahepatic biliary tree (intrahepatic cholangiocarcinoma) or from the junction, or adjacent to the junction, of the right and left hepatic ducts (hilar cholangiocarcinoma). "Targeting PDGFRα by imatinib sensitized cholangiocarcinoma cells to apoptotic stimuli in vitro and in vivo." (PMID 24359404, 2013). "PDGF-A and PDGFRα mRNA and protein are often overexpressed in patients with cholangiocarcinoma; treatment of cholangiocarcinoma cell lines with the PDGF receptor kinase inhibitors imatinib or sunitinib suppressed cell viability and migration." (PMID 24359404, 2013).
clear cell adenocarcinoma (2 papers, 2012 to 2020). A malignant neoplasm composed of glandular epithelial clear cells.
colorectal tumor (2 papers, 2020 to 2025). "It was shown that Imatinib (PDGFRα inhibitor) can reduce the aggressive phenotype of CMS4 class colorectal tumors." (PMID 33213472, 2020). "It was demonstrated that the combination of PDGFR and EGFR inhibitors (imatinib versus cetuximab) in colorectal tumor graft with mutant PDGFRA R981H (exon 22), identified as a mechanism of primary resistance to EGFR blockade, has a strong anti-tumor activity but with a short-lived effect." (PMID 33213472, 2020).
Crohn disease (2 papers, 2019 to 2022). A gastrointestinal disorder characterized by chronic inflammation involving all layers of the intestinal wall, noncaseating granulomas affecting the intestinal wall and regional lymph nodes, and transmural fibrosis. "In summary, we identified ADAMDEC1 as a novel marker for intestinal inflammation and Crohn’s disease and it is selectively expressed in colonic mucosal PDGFRα+ cells." (PMID 35563399, 2022). "Additionally, ADAMDEC1 was detected through immunohistochemistry within PDGFRα+ cells in Crohn’s disease-affected colonic mucosa." (PMID 35563399, 2022). "Our data suggest that study of the expression of ADAMDEC1 should be focused on PDGFRα+ cells in Crohn’s disease patients, and not in macrophages." (PMID 35563399, 2022). "Additionally, overexpression of both ADAMDEC1 mRNA and protein was consistently observed in PDGFRα+ cells, but not in CD64+ macrophages found in human colonic mucosal tissue affected by Crohn’s disease." (PMID 35563399, 2022).
demyelination (2 papers, 2015 to 2026). "In our study, PDGFRα-positive and NG2-positive OPCs increased in the cortex of mice subjected to CPZ-induced demyelination." (PMID 25815032, 2015).
dysembryoplastic neuroepithelial tumor (2 papers, 2023). A benign glial-neuronal neoplasm. "Dysembryoplastic neuroepithelial tumors (DNETs) harbored alterations in MAPK/PI3K pathway genes, as was previously reported, including FGFR1 (21%, 4/19), PDGFRA (10%, 2/19), and BRAF (5%, 1/19)." (PMID 37492101, 2023).
dyslipidaemia (2 papers, 2023 to 2024). "Pdgfrα-cre driven KO of Alms1 (MSC KO) recapitulated insulin resistance, fatty liver, and dyslipidaemia in both sexes." (PMID 38583571, 2024).
emphysema (2 papers, 2018 to 2025). "Ablation of Pdgfrα+ cells led to emphysema-like enlargement of distal airspaces during embryogenesis, resulting in defective alveolar structure and function." (PMID 39878483, 2025).
encephalitis (2 papers, 2022 to 2025). An acute inflammatory process affecting the brain parenchyma. "Recombinant astrovirus strains carrying mink-derived capsid segments demonstrate expanded organotropism, leveraging upregulated platelet-derived growth factor receptor alpha (PDGFRα) to infect human neural progenitor cells, resulting in extra-intestinal manifestations such as encephalitis." (PMID 41347242, 2025).
fibrous tumors (2 papers, 2016 to 2024). "Later on, there were reports of gastrointestinal CD34+ ‘fibrous tumors’ with an uncertain classification in the presence of a germline PDGFRA mutation." (PMID 38305808, 2024). "A PDGFRA-mutant family bearing intestinal tumors defined as GISTs, but lacking GIST hallmarks except PDGFRA status, has also been reported; these tumors are probably fibrous tumors, possible variants of another GI PDGFRA-driven tumor: inflammatory fibroid polyp (IFP)." (PMID 27437068, 2016).
gastroparesis (2 papers, 2013 to 2019). Paralysis of the muscles of the stomach wall resulting in delayed emptying of the gastric contents into the small intestine. "We also observed an increase in mRNAs encoding contractile proteins in the gastric muscularis of subjects with idiopathic gastroparesis and confirmed our previously reported decreases in mRNAs associated with PDGFRα-positive fibroblasts in these subjects." (PMID 31221130, 2019). "Using qRT-PCR of RNA isolated from the stomach muscularis of control and gastroparesis patients we previously reported that idiopathic gastroparesis is associated with altered smooth muscle cell contractile protein expression and loss of PDGFRα+ cells without a change in ICC." (PMID 31221130, 2019). "In the context of GI tract pathophysiology, the possible involvement of TC has been investigated in human gastroparesis, but no changes in shape, location and number of PDGFRα-positive cells were reported." (PMID 24151977, 2013).
gliosarcoma (2 papers, 2021 to 2022). A rare histological variant of glioblastoma (WHO grade IV) characterized by a biphasic tissue pattern with alternating areas displaying glial and mesenchymal differentiation (WHO).
hemorrhagic stroke (2 papers, 2015 to 2017). A stroke caused by a bleed on the brain. "Similar results have been obtained by blocking PDGFRα signaling in animal models of hemorrhagic stroke, spinal cord injury, MS, and seizures." (PMID 26500491, 2015).
Hernia (2 papers, 2020 to 2025). "The use of PDGFRA-cre mice facilitated the selective ablation of ESR1 in PDGFRA+ FAPs, underscoring the sufficiency of these cells in the fibrotic processes associated with hernias." (PMID 39903526, 2025). "To discern the impact of ESR1 signaling on LAM HAFs and hernia development, we engineered a fibroblast-specific ESR1 knockout in Aromhum mice (fEsr1–/– Aromhum) by cross-breeding floxed ESR1, PDGFRA-cre, and Aromhum mice." (PMID 39903526, 2025). "The percentage of HAFs marked by expression of PDGFRA and ESR1 was significantly lower in the hernia-free fEsr1–/– Aromhum mice compared with the positive control herniated fEsr1+/+ Aromhum mice (1.8% vs. 32.3%)." (PMID 39903526, 2025). "Thus, we hypothesize that HAFs, a subset of PDGFRA+ fibroblasts (FAPs), possibly activated by E2/ESR1 signaling, play an essential role in hernia formation in Aromhum mice." (PMID 39903526, 2025).
Hydrocephalus (2 papers, 2021 to 2022). Hydrocephalus is an active distension of the ventricular system of the brain resulting from inadequate passage of CSF from its point of production within the cerebral ventricles to its point of absorption into the systemic circulation. "Previous studies have identified quantitative proteomics signatures in post-hemorrhagic hydrocephalus and idiopathic normal pressure hydrocephalus, these finding suggests that TLR4-NF-κB, mTOR, PDGFRα signaling and other pathways play an important role in hydrocephalus." (PMID 36052359, 2022).
infarction (2 papers, 2015 to 2020). A localised pathological necrosis of tissue resulting from obstruction of the blood supply usually by a thrombus, an embolus, or vascular torsion. "In addition, intravital imaging revealed that more GFP+/PDGFRα+ cells were recruited to the peri-infarction area in the HMGB1 group than in the control 12 h after treatment." (PMID 32275672, 2020).
intestinal tumors (2 papers, 2016 to 2020). "Poorly infiltrated GISTs, primarily KIT/PDGFRA WT intestinal tumors, showed activation of Hedgehog and WNT/β-catenin immune excluding pathways." (PMID 33048845, 2020).
intrahepatic cholangiocarcinoma (2 papers, 2023). A carcinoma that arises from the intrahepatic bile duct epithelium in any site of the intrahepatic biliary tree. "Multiplex-IF of intrahepatic cholangiocarcinoma revealed stromal protein gradients similar to those observed in CRLM, which were characterized by ASMA, NGFR, and PDGFRa at the outer edge, and FAP and PDGFRb at the inner side of the rim." (PMID 37596278, 2023).
lipodystrophy (2 papers, 2020 to 2023). A congenital or acquired disorder characterized by abnormal loss or redistribution of the adipose tissue in the body. "Our results suggest that adding MCP-1 to PRP may provide a valuable therapeutic approach to increase fat graft survival and adipogenesis in lipodystrophy patients by increasing PDGFRα and decreasing IL-10 expression of adipose tissue." (PMID 38003291, 2023). "Although the exact mechanism by which Nck1 deficiency enhances PDGFRα activation remains to be elucidated, our findings are consistent with the fact that constitutive activation of PDGFRα inhibits WAT development and leads to lipodystrophy in mice." (PMID 32059739, 2020).
lipoma (2 papers, 2012 to 2024). A benign, usually painless, well-circumscribed lipomatous tumor composed of adipose tissue. "On the other hand, in families with germline PDGFRA mutations, multiple GISTs develop only in the stomach, and inflammatory fibroid polyps or lipomas also develop in some cases." (PMID 38609732, 2024). "This patient’s alternative germline PDGFRA mutation may have resulted in her slightly different phenotype as she was noted to have, in addition to gastric GISTs, multiple lipomas and fibrous tumors of her small intestine." (PMID 23036227, 2012). "Lipomas and fibrous tumors of the small intestine were not previously part of other families described with PDGFRA mutations and predisposition to GIST nor where they a feature of families with KIT germline mutations." (PMID 23036227, 2012).
myelofibrosis (2 papers, 2023 to 2024). A partial or complete replacement of the bone marrow stroma by fibrous tissue. "MSCs contained platelet-derived growth factor receptor alpha (PDGFRα) which is necessary for myelofibrosis." (PMID 39523306, 2024). "Therefore, targeting the PDGFRα pathway in MSCs may be beneficial in treating myelofibrosis." (PMID 39523306, 2024).
myeloid sarcoma (2 papers, 2015 to 2022). A tumor mass composed of myeloblasts or immature myeloid cells. "We present an unusual case of a PDGFRA‐rearranged myeloid sarcoma with associated bone marrow involvement by a PDGFRA‐rearranged chronic myeloid neoplasm." (PMID 36051048, 2022).